LINC00621 (long independently transcribed non-coding RNA 621)
Gene: Long non-coding RNA gene on chromosome 13 (22,859,050 to 22,916,466, reverse strand). Ensembl gene ENSG00000262619.
Diseases named in the same sentence as LINC00621 in open-access papers:
LINC00621 is named in the same sentence as 1 disease in open-access papers, as found by Europe PMC text mining. Sharing a sentence is not in itself a finding about the gene and the disease. The quoted sentences say what the papers report.
tumor (1 paper, 2023). "The impression of LINC00621 knockdown on LUAD tumor growth and metastasis put into effect by murine models." (PMID 37277890, 2023). "Taking all the results together, we discovered that LINC00621 elevates the tumor cell invasion and tumor metastasis capacity in LUAD." (PMID 37277890, 2023). "Therefore, our study uncovered that LINC00621 is a tumor‐promoting factor in LUAD." (PMID 37277890, 2023).